CCL17 (C-C motif chemokine ligand 17)
Diseases named in the same sentence as CCL17 in open-access papers (continued):
Sharing a sentence is not in itself a finding about the gene and the disease.
prostate carcinoma (6 papers, 2016 to 2024). A carcinoma that arises from epithelial cells of the prostate gland. "Here, we show that Tregs in the tumor microenvironment are associated with poor prognosis in dogs with spontaneous prostate cancer, and that there is a link between Treg migration and C-C chemokine ligand 17 (CCL17)–CCR4 pathway." (PMID 35131860, 2022). "High expression of CCL17 has been linked to worse prognosis in prostate cancer, renal cancer, and testicular cancer, and increased expression has also been observed in chronic viral infections such as hepatitis C and human papillomavirus, which are associated with malignant transformation." (PMID 34937192, 2021). "The migration and invasion of prostate cancer cells via enhanced phosphorylation of Akt were promoted by CCL17 and CCL22." (PMID 28039457, 2017). "CCL22 and CCL17 were M2-type macrophage markers, and U937-M cells took on the characteristics of M2-type macrophages after co-culture with prostate cancer cells." (PMID 28039457, 2017). "Inhibition of the CCL2–CCR2 or CCL17/CCL22–CCR4 axis by specific antagonists of CCR2 or CCR4 clearly showed suppression of the migration ability of prostate cancer cells." (PMID 28039457, 2017). "The CCL17 concentration increased in urine but not in blood, suggesting that CCL17 produced locally in prostate cancer leaks into urine and is associated with the abundance of tumor-infiltrating Tregs." (PMID 35131860, 2022). "Urinary CCL17 concentration was increased in dogs with prostate cancer." (PMID 35131860, 2022). "High mRNA expression of CCL17, CCL22, CCR4, and Foxp3 was detected in 5.0%, 3.0%, 2.2%, and 5.0% of patients with prostate cancer, respectively." (PMID 35131860, 2022). "We searched for mRNA expression of CCL17, CCL22, CCR4, and Foxp3 in the publicly available transcriptomic dataset of human prostate cancer from TCGA PanCancer Atlas (n=493)." (PMID 35131860, 2022). "Next, the effects of CCL17 and CCL22 on prostate cancer cells were analyzed using a transwell migration assay and a wound-healing assay." (PMID 28039457, 2017). "CCR2 and CCR4 antagonists clearly inhibited the migration ability of prostate cancer cells, which was induced by CCL2 and CCL17/CCL22." (PMID 28039457, 2017). "TAMs have been reported to secrete M2-type macrophage markers, including both CCL17 and CCL22; therefore, our study focused on the CCL17/CCL22–CCR4 axis with regard to interactions between TAMs and prostate cancer cells." (PMID 28039457, 2017). "Herein, we report that TAMs promote prostate cancer progression through the activation of the CCL2–CCR2 axis, followed by the activation of the CCL17/CCL22–CCR4 axis." (PMID 28039457, 2017). "Quantitative real-time PCR showed approximately 700-fold increase in the expression of CCL17 gene in prostate cancer compared with the expression in normal canine prostate." (PMID 35131860, 2022). "Moreover, AZD5363, a potent inhibitor of Akt, inhibited CCL17- and CCL22-induced prostate cancer migration." (PMID 28039457, 2017). "We hypothesized that prostate cancer cells utilize the CCL2–CCR2 and CCL17/CCL22–CCR4 axes to metastasize through interactions between TAMs and prostate cancer cells." (PMID 28039457, 2017). "We hypothesized that prostate cancer cells also utilize the CCL2–CCR2 axis and the subsequent CCL17/CCL22–CCR4 axis to metastasize." (PMID 28039457, 2017). "For example, chemokine ligand 17 (CCL17), promotes the stemness, EMT process, the TGF-β1 and Wnt/β-catenin signaling in MHCC97L cells; chemokine (C-X3-C motif) ligand 1 (CX3CL1), participates in the molecular events that regulate cell adhesion, migration and survival of human prostate cancer cells." (PMID 27258544, 2016). "However, to our knowledge, the expression and role of CCR4 in prostate cancer have not been reported so far, and little is known about the relationship between TAMs and the CCL2–CCR2 and CCL17/CCL22–CCR4 axes with regard to tumor migration and invasion in prostate cancer." (PMID 28039457, 2017).
Sepsis (6 papers, 2015 to 2025). Sepsis is defined as life-threatening organ dysfunction caused by a dysregulated host response to infection. "Among these upregulated genes, prior research demonstrated that Nr4a2 has been linked to M2 polarization and protection in sepsis models, while Ccl17 and Csf1 are implicated in the recruitment of Th2 cells." (PMID 41026710, 2025). "In a mice sepsis model, it was suggested that CCL17 through its receptor CCR4+ on Tregs has prolonged immunosuppressive effects." (PMID 40076848, 2025). "Furthermore, colon ascendens stent peritonitis (CASP)-induced sepsis in mice has been shown to increase CCL17 and CCL22 mRNA levels in the spleen and liver." (PMID 26197455, 2015). "In this study, we investigated the role of CCR4, the CCL17/CCL22 chemokine receptor, in the innate and acquired immune responses during severe sepsis and the role of Tregs in effecting the outcome." (PMID 26197455, 2015). "In our first set of experiments, we demonstrated that CCR4, the receptor for CCL17 and CCL22, contributes to the establishment of an inadequate innate immune response during severe sepsis." (PMID 26197455, 2015).
systemic lupus erythematosus (6 papers, 2013 to 2022). An autoimmune multi-organ disease typically associated with vasculopathy and autoantibody production. "In addition, in the lupus model of NZB/W F1 mice, increased CCL17 levels were detected." (PMID 34831390, 2021).
glioma (5 papers, 2021 to 2025). A benign or malignant brain and spinal cord tumor that arises from glial cells (astrocytes, oligodendrocytes, ependymal cells). "HIF-2α inhibition may regulate the recruitment of Tregs to the glioma site through a reduction of Treg-attracting chemokines such as CCL17, CCL22, and CCL18 or a re-polarization of the pro-tumoral macrophages secreting these factors." (PMID 40095115, 2025). "Moreover, OAT-1746 treatment affects the expression of genes involved in leukocyte chemotaxis (Ccl2, Ccl7, Ccl17) and supporting glioma migration and invasion (Cme1, S100a4 and Mmp14)." (PMID 34504786, 2021). "In high-grade glioma, deletion of SOX7 reduced CCL17, CCL22, and CCL5, which subsequently decreased Treg cells, while deletion of SOX17 increased CCL17 concentration and recruitment of Treg cells." (PMID 38331879, 2024).
heart failure (5 papers, 2019 to 2025). Inability of the heart to pump blood at an adequate rate to meet tissue metabolic requirements. "Our findings reveal that chemokine CCL17 is identifiable as a novel therapeutic target in age-related and Ang II–induced pathological cardiac hypertrophy and heart failure." (PMID 35687056, 2022). "Importantly, CCL17 is also a potential novel treatment target for age-related diseases, cardiac hypertrophy, and heart failure." (PMID 37940228, 2023). "Serum proteomic profiling of an age-stratified healthy population and further community-based cohort together with heart failure patients study demonstrated that circulating C-C motif chemokine ligand 17 (CCL17) level increased with age and correlated with cardiac dysfunction." (PMID 35687056, 2022). "Our findings suggest that cardiac chagasic patients have an increased percentage of inflammatory monocytes and produce more IL-6, a biomarker of heart failure and left ventricular dysfunction, whereas asymptomatic chagasic individuals present a higher percentage of reparative monocytes and CCL17." (PMID 31379862, 2019).
lung diseases (5 papers, 2021 to 2025). "The CCL17-CCR4 axis is implicated in IPF progression, suggesting potential benefits from targeting CCL17 or CCR4 in fibroproliferative lung diseases." (PMID 39768150, 2024). "CCL17 promotes the recruitment, activation, and development of Th2-polarized cells expressing CCR4 and plays an essential role in the development of lung diseases." (PMID 35743888, 2022).
nasal polyp (5 papers, 2015 to 2023). "Th2 cytokines, such as IL-4 and IL-13, upregulate CCL17 expression in nasal polyp epithelium, whereas Th1 cytokines increase CCL17 levels in both normal and nasal polyp epithelium." (PMID 37762530, 2023). "The stimulation of cultured epithelial cells with Th2 cytokines, IL-4 and IL-5, resulted in higher CCL17 expression in nasal polyp epithelial cells when compared to normal ethmoid tissue." (PMID 35455762, 2022). "Thus, we aimed to evaluate the expression of CCL17 and its regulation by Th cytokines in nasal polyp (NP) epithelial cells." (PMID 29746583, 2018). "However, the association between the epithelial barrier and CCL17 expression has not been studied in chronic rhinosinusitis with nasal polyp (CRSwNP)." (PMID 29746583, 2018).
Obesity (5 papers, 2023 to 2025). Accumulation of substantial excess body fat. "We have reported using gene-deficient male mice that CCL17 is involved in pain-like behaviour and disease in a number of OA mouse models in lean mice and that this involvement is conserved in obesity-exacerbated OA models." (PMID 39820104, 2025). "Furthermore, we found that obesity and females was associated with response to dupilumab treatment; CCL17/TARC showed the strongest correlation with the improvement in clinical scores among patients aged <18 years." (PMID 37153599, 2023). "Recently, evidence was provided, using gene-deficient mice, for the involvement of the GM-CSF/CCL17 pathway in the development of pain-like behaviour and maximal disease in three experimental OA models, as well as for the exacerbated OA development due to obesity." (PMID 39820104, 2025). "Based on these data, we explored the effects of anti-CCL17 mAb therapy on these obesity comorbidities." (PMID 39820104, 2025). "Future in vivo studies in an animal model of obesity are required to delineate the potential benefit of altering the CCR4/CCL17/CCL22 signalling in vivo and assess the therapeutic window of CCR4 inhibition." (PMID 37124725, 2023). "Together, these data suggest that CCL17 does not regulate body mass gain or obesity-associated metabolic changes in mice fed a HFD." (PMID 39820104, 2025). "In an attempt to gain insights as to whether CCL17 could be involved in obesity-induced metabolic changes, we used the highest dose of B293 tested in this study in a model of HFD-induced obesity." (PMID 39820104, 2025). "Based on the data presented, CCL17 could be a therapeutic target in OA patients with joint injury alone or with obesity." (PMID 39820104, 2025). "Specifically, obesity-induced knee joint damage was found to be dependent on GM-CSF and CCL17, independent of CCL22." (PMID 41291326, 2025). "This pathway promotes neuronal sensitization through CCR4-expressingcells and affects obesity-related pain symptoms.In OA pain, GM-CSF triggers inflammation via the GM-CSF/Jmjd3/IRF4/CCL17 pathway, and theinhibition of CCL17 ameliorates GM-CSF-induced inflammatory pain, arthritic pain, anddiseases." (PMID 39463202, 2024). "Taken together, our findings strongly suggest that the ERK1/2 signaling pathway could be involved in CCL17 and CCL22 effects in obesity-related endothelial dysfunction." (PMID 37124725, 2023). "Our results of elevated CCL17 and CCL22 levels in peripheral blood from morbidly obese patients suggest that these chemokines may play a role in leukocyte trafficking and endothelial dysfunction in obesity, in addition to their role as chemoattractants in the adipose tissue milieu." (PMID 37124725, 2023).
pituitary adenoma (5 papers, 2021 to 2025). "CCL17 secreted by tumor-associated macrophages could promote pituitary adenoma invasion by enhancing the mTORC1 signaling pathway." (PMID 37563740, 2023). "In pituitary adenoma, lactate activates the mTOR pathway in TAMs, leading to increased secretion of C-C motif chemokine ligand 17 (CCL17), which binds to C-C motif chemokine receptor 4 (CCR4) on tumor cells and promotes invasion." (PMID 41152975, 2025). "In pituitary adenoma, lactate-induced M2-TAMs promote pituitary adenoma invasion via secreting CCL17." (PMID 38576043, 2024).
Anxiety (4 papers, 2021 to 2024). Intense feelings of nervousness, tension, or panic often arise in response to interpersonal stresses. "In addition, compared with their control WT littermates, aged Ccl17-KO mice exhibited increased motor function and locomotor activity (left), reduced anxiety-like behavior (right), and improved spatial working memory." (PMID 35687056, 2022). "Similarly, chemokines such as ENA-78/CCL5, GROα/CXCL1, MCP-1/CCL2, and TARC/CCL17 were increased in women displaying high anxiety levels." (PMID 34863117, 2021). "TARC/CCL17 and Eotaxin/CCL11 showed significant associations with high scores for depression (p < 0.04) whereas, MCP-1/CCL2 and MIP-1α/CCL3 were significantly associated with high scores for anxiety (p < 0.05) in the ANX + DEP group." (PMID 34863117, 2021).
breast tumor (4 papers, 2015 to 2025). "Decreased TRIM24 expression and increased expression of the M2 genes CCL17 and IRF4 were detected in macrophages isolated from breast tumors compared with their levels in adjacent normal tissues." (PMID 31554795, 2019). "Notably, upregulation in these patients was largely restricted to A2AR, 2B4, and CCL17, suggesting the potential involvement of alternative pathways in regulating CD4+ T cell function within siglec-7 high breast tumor microenvironment." (PMID 40547037, 2025). "Similarly, Gobert and colleagues found a strong correlation between infiltrating Foxp3+ Treg cells and CCL22, but not with CCL17, in breast tumor." (PMID 26020249, 2015).
Crohn disease (4 papers, 2009 to 2025). A gastrointestinal disorder characterized by chronic inflammation involving all layers of the intestinal wall, noncaseating granulomas affecting the intestinal wall and regional lymph nodes, and transmural fibrosis. "For instance, CCL17 expression is also observed in several human type 1 inflammatory diseases, including ulcerative colitis, Crohn’s disease and rheumatoid arthritis, emphasising that CCL17 can be present in other inflammatory contexts." (PMID 41159038, 2025). "CCL17 is also over-expressed in stromal, endothelial and epithelial tissues in autoimmune disorders including the inflammatory bowel diseases, Crohn's disease and ulcerative colitis (UC)." (PMID 19692448, 2011).
cutaneous T-cell lymphoma (4 papers, 2018 to 2024). "The pathogenic role of CCL17/TARC was suggested in skin diseases such as AD, cutaneous T-cell lymphoma, bullous pemphigoid, scabies and drug eruption." (PMID 36362116, 2022). "Elevated serum CCL17 is seen in other inflammatory skin conditions including bullous pemphigoid and cutaneous T-cell lymphoma." (PMID 38558806, 2024). "CCL17 has been reported to be related to the development of several other diseases such as cutaneous T-cell lymphoma (CTCL), asthma, and acute eosinophilic pneumonia." (PMID 33670758, 2021).
epilepsy (4 papers, 2012 to 2025). A brain disorder characterized by episodes of abnormally increased neuronal discharge resulting in transient episodes of sensory or motor neurological dysfunction, or psychic dysfunction. "On the other hand, our study and the previous ones used different promoters to drive DTR expression, and it may be that only the selective death of CCL17‐positive neurons results in epilepsy." (PMID 39607395, 2025). "Hence, expression of the DTR under control of the Ccl17 promoter region would allow examination of the effects of selective pyramidal neuron ablation on brain function and epilepsy development." (PMID 39607395, 2025). "To examine the effects of selective pyramidal neuron depletion in the hippocampus on brain functioning and epilepsy development, we generated a mouse line expressing the simian DTR under control of the Ccl17 promoter, which is expressed in a subset of hippocampal CA1 pyramidal neurons in mice." (PMID 39607395, 2025). "In addition, we find that the ratio of TARC (thymus and activation regulated chemokine, CCL17) to sICAM5 constitutes a compelling candidate proteomic signature for treatment-resistant epilepsy." (PMID 23293627, 2012).
experimental autoimmune encephalomyelitis (4 papers, 2020 to 2022). An autoimmune demyelinating disease of the central nervous system that is produced experimentally in animals by the injection of homogenized brain or spinal cord in Freund's adjuvant. "The STAT5 tetramers were showed to promote the pathogenesis of experimental autoimmune encephalomyelitis, and the production of CCL17 was regulated by GM-CSF-mediated STAT5 tetramerization through monocyte-derived cells in the STAT5 tetramer-deficient N-domain double knockout mouse." (PMID 36138889, 2022). "The importance of CCR4 and its two ligands, TARC (CCL17) and CCL22, has also been noticed in central nervous system autoimmunity and studied in the experimental autoimmune encephalomyelitis murine model." (PMID 34539561, 2021). "The evidence is consistent for the involvement of CCL17, CCL22 and CCR4 in the experimental autoimmune encephalomyelitis model of MS72–74." (PMID 32179746, 2020).
helminth infection (4 papers, 2018 to 2022). "TARC is a serological indicator of multiple helminth infections and higher CCL17 levels reflect immune activation of basophils, eosinophils, and macrophages." (PMID 35503786, 2022). "Thus, gene expression profiles of macrophages imprinted during helminth infection at least partially overlap with profiles of allergen-trained macrophages, which also show increased CCL17 responses and integrin expression." (PMID 36065058, 2022).